ELMOD1 (ELMO domain containing 1)
Description:
Acts as a GTPase-activating protein (GAP) toward guanine nucleotide exchange factors like ARL2, ARL3, ARF1 and ARF6, but not for GTPases outside the Arf family.
Synonyms: DKFZp547C176
Tractability: PROTAC: ubiquitination databases record sites on it; its protein half-life has been measured.
Gene: Protein-coding gene on chromosome 11 (107,591,091 to 107,666,779, forward strand). Ensembl gene ENSG00000110675.
Subcellular location (Human Protein Atlas): Nucleoplasm; Cytosol; Vesicles
Gene Ontology:
Molecular function: GTPase activator activity
Biological process: cilium assembly
Cellular component: cilium; Golgi apparatus; synapse; glutamatergic synapse
Genetic constraint (gnomAD): Loss-of-function variants: 15 observed, 34.75 expected, observed/expected ratio (o/e) 0.43, 90% interval 0.29 to 0.67. The upper end of that interval is the gene's LOEUF score, 0.67, which puts it in group 2 of 6, group 1 being the genes least tolerant of losing a copy. Missense variants: 273 observed, 326.14 expected, observed/expected ratio (o/e) 0.84, 90% interval 0.76 to 0.93. Synonymous variants: 100 observed, 112.13 expected, observed/expected ratio (o/e) 0.89, 90% interval 0.76 to 1.05.
Homologues: Orthologues: chimpanzee ELMOD1 (99% identical), macaque ELMOD1 (99% identical), pig ELMOD1 (98% identical), rabbit ELMOD1 (98% identical), dog ELMOD1 (97% identical), guinea pig ELMOD1 (95% identical), mouse Elmod1 (94% identical), rat Elmod1 (93% identical), tropical clawed frog elmod1 (79% identical), zebrafish elmod1 (75% identical). Paralogues in human: ELMOD2 (47% identical), ELMO1 (21% identical), ELMO3 (21% identical), ELMO2 (20% identical), ELMOD3 (18% identical).
Diseases named in the same sentence as ELMOD1 in open-access papers:
ELMOD1 is named in the same sentence as 6 diseases in open-access papers, as found by Europe PMC text mining. Sharing a sentence is not in itself a finding about the gene and the disease. The quoted sentences say what the papers report.
deafness (6 papers, 2012 to 2023). An inherited or acquired condition characterized by the complete loss of the ability to hear from one or both ears. "By contrast, Elmod1 is a poorly characterized gene, only recently associated with hair cell stereocilia dysmorphology and deafness in mice." (PMID 39195995, 2022). "We found that Elmod1 expression localized to both cochlear and vestibular hair cells of the inner ear, consistent with hair cell dysfunction being the underlying cause for the deafness and balance dysfunction of Elmod1 mutant mice." (PMID 22558334, 2012). "Here, we describe two independent spontaneous inactivating mutations of the mouse Elmod1 gene that cause deafness and balance defects." (PMID 22558334, 2012). "Mutations in ELMOD1 caused deafness and hair cell dysfunction in mice." (PMID 37997996, 2023). "Recently, two spontaneous mutations (rda and rda2J) in mouse Elmod1 were shown to result in profound deafness and vestibular dysfunction, demonstrating that the function of ELMOD1 is essential for regulating the shape and maintenance of inner ear hair cell stereocilia in mice." (PMID 24039609, 2013). "Unlike the Elmod1 mutant phenotype, however, the effects of Diap3 overexpression are remarkable both for the late onset of deafness and for the preservation of OHCs as compared to IHCs." (PMID 23441200, 2013).
colorectal cancer (1 paper, 2022). A primary or metastatic malignant neoplasm that affects the colon or rectum. "In addition, these hypermethylated genes, mainly PRDM14, RALYL, ELMOD1, and TMEM132E, were validated and confirmed in colorectal cancer by using publicly available DNA methylation data." (PMID 35065650, 2022). "MeDIP-seq can be used as an optimal approach for analyzing cfDNA methylomes, and 12 probes of four differentially methylated genes identified by MeDIP-seq (PRDM14, RALYL, ELMOD1, and TMEM132E) could serve as potential biomarkers for clinical application in patients with colorectal cancer." (PMID 35065650, 2022).
gastric cancer (1 paper, 2022). A primary or metastatic malignant neoplasm involving the stomach.
metastatic melanoma (1 paper, 2012). A melanoma that has spread from its primary site to another anatomic site. "The expression levels of UBE2S and TMC01 but not ELMOD1 RNA in metastatic melanomas appear to be significantly associated with the survival of patients." (PMID 22536322, 2012).
ELMOD1 also shares sentences with these, for which no sentence is quoted: tumor (2 papers); melanoma (1).